COL6A1 (collagen type VI alpha 1 chain)
Diseases named in the same sentence as COL6A1 in open-access papers (continued):
Sharing a sentence is not in itself a finding about the gene and the disease.
tumor (continued). "Second, tumor subsets enriched for microenvironment features, including hypoxia markers (e.g., Slc2a1, Pdk1, Car9), extracellular matrix (ECM) genes (e.g., Matn2, Fn1, Dcn, Col6a1), vasculature (e.g., Cdh5, Pecam1, Vwf), and interferon response genes (e.g., Rsad2, Ifit3, Gbp3, Cxcl10, Cd274)." (PMID 40171265, 2025). "Analysis of a large genomic patient dataset revealed that the SLRPs lumican, fibromodulin and decorin as well as COL1A1 and COL6A1 all correlate with good overall survival in SHH MB patients; suggesting that the presence of this ECM shell in SHH tumours may be a reliable biomarker of good outcome." (PMID 36631900, 2023). "In particular, COL6A1 was notably abundant, suggesting that it is possible that ECM components may be secreted into the ECM by stromal cells rather than tumour cells, which could account for the reduced abundance seen in 2D cell cultures compared to primary 3D tumor tissues." (PMID 40517137, 2025). "We compared the transcriptome data between normal samples and GBM tumor samples, which indicated that ANXA1, PDPN, COL6A1, BCL3, RUNX1, and WWTR1 were upregulated and compared to normal samples, BCL11A was downregulated in GBM tumor samples." (PMID 37434432, 2023). "Conversely, 26 genes, including mediators of epithelial–mesenchymal transition (i.e., COL6A1/A2, COL16A1, MFAP5, MMP11), were co-expressed in tumor tissue but not in NAU." (PMID 35626146, 2022). "Consistently, single-cell RNA-seq analysis of nonmalignant tumor tissues and HGOSC tissues was utilized to investigate the distribution of SFRP2 in TME and a novel subset with the highest enrichment of SFRP2 and CAF markers (COL6A1, COL6A2, FAP) was identified." (PMID 38069266, 2023).
cancer (52 papers, 2007 to 2026). A tumor composed of atypical neoplastic, often pleomorphic cells that invade other tissues. "In this study, we analyzed the properties of Col6a1-positive fibroblasts in colitis-associated cancer." (PMID 38203319, 2023). "The results revealed that COL6A1/2/3 were prognostic risk factors with HR > 1 in multiple cancer types." (PMID 36167487, 2022). "Most interestingly, we found that exosomal COL6A1 derived from OS cells convert normal fibroblasts to cancer-associated fibroblasts (CAFs) by secreting pro-inflammatory cytokines, including IL-6 and IL-8." (PMID 33391546, 2021). "COL6A1 expression was associated with the 14 functional states in 15 cancer types." (PMID 37434432, 2023). "Additionally, COL6A1 can be transported by exosomes and influence the differentiation of normal fibroblasts into cancer-associated fibroblasts." (PMID 38031074, 2023). "The highest expression of genes encoding Col1a1-2, Col3a1, Col4a1, Col4a2, Col5a1, Col5a2, Col6a1, Col8a1, Col9a3, Col10a1, Col12a1, Col14a1, Col15a1, Col16a1, Col18a1, and Col28a1 were detected in untreated tumors, whose landscapes were dominated by Krt8+ cancer cells." (PMID 39372930, 2024). "Previous studies have indicated that COL6A1 promotes migration and invasion in various cancers, including lung cancer, renal cancer, prostate cancer, cervical cancer, and osteosarcoma." (PMID 40025063, 2025). "COL6A1, a major ECM protein, has been implicated in promoting migration and invasion in various cancers." (PMID 40025063, 2025). "Several studies have demonstrated that high expression of COL6A1 correlates with poor prognosis in various cancers." (PMID 38887185, 2024). "We next compared COL6A1 expression in 21 cancer cell lines across the 15 cancer types, in which the GBM cancer cell lines exhibited a high COL6A1 expression." (PMID 37434432, 2023). "Despite these significant differences, Col6a1+ and Col6a1− fibroblasts displayed similar pro-tumorigenic properties in both in vitro co-culture assays with cancer organoids and in vivo allograft experiments." (PMID 38203319, 2023). "For instance, increased expression of COL6A1, SDC4, FRAS1, AGRN, and COL4A2 has been observed in different cancer types and reported to be associated with metastasis and poor outcomes in patients." (PMID 37987316, 2023). "Taken together, our results show that both Col6a1+ and Col6a1− IMCs can support cancer growth in vitro and in vivo." (PMID 38203319, 2023). "To further understand the potential molecular mechanism of COL6A1/2/3 in cancers, we first identified the effects of methylation patterns of COL6A1/2/3 in pan-cancer by GSCALite." (PMID 36167487, 2022). "Another essential finding has suggested that COL6A gene expression levels were correlated with immune subtypes in pan-cancer, and COL6A1/2/3 all have the highest expression in the C6 immune subtype, which has the worst prognosis among the six immune subtypes." (PMID 36167487, 2022). "Our results indicated striking inter-cancer heterogeneity in the expression levels of COL6A1/2/3 in pan-cancer." (PMID 36167487, 2022). "We further investigated the relationship between the expression levels of COL6A1/2/3 and infiltrating stromal cells and immune cells in 33 cancers." (PMID 36167487, 2022). "Based on public resources and bioinformatics analyses, the similarities and differences in molecular feature and clinical significance of COL6A members, especially COL6A1/2/3, were comprehensively analyzed in pan-cancer." (PMID 36167487, 2022). "This research showed the similarities and differences of molecular characteristic in collagen VI family in pan-cancer, especially COL6A1/2/3." (PMID 36167487, 2022). "We further conducted coexpression analysis of COL6A members in pan-cancer, and found that COL6A1, COL6A2 and COL6A3 were highly positively correlated." (PMID 36167487, 2022).
cancer (continued). "In spontaneous models of tumorigenesis, mice with Col6a1+ fibroblast-specific deletions of Tlr4, Myd88, or Ptgs2 (encodes an enzyme important for PGE2 production) exhibit reduced cancer development." (PMID 36591258, 2022). "Many important components of ECM, which were differentially expressed in cluster 1 or 2, such as COL6A1, COL1A1, and COL3A1, are mainly secreted by cancer-associated fibroblasts (CAF)." (PMID 33508502, 2021). "As a proof of principle, we established a Col6a1 knockout MCA205 cell line and found that Col6a1 deficiency in cancer cells significantly increased cytokine secretion and immune cell infiltration." (PMID 34782761, 2021). "For example, the expression of COL6A3 and COL6A1 was upregulated in most cancer types compared with controls, which play an important role in regulating the tumorigenesis and metastasis of cancer." (PMID 31627190, 2019). "Two recent secretome studies reported that secreted Col6a1 levels are increased for several strongly metastatic cancer cell lines relative to their less-metastatic counterparts." (PMID 29924804, 2018). "We report that all of the studied collagen types (COL1A1, COL3A1, and COL6A1) in the AT, to be modulated by cancer cachexia." (PMID 28288584, 2017). "In the Cancer Signaling Phospho Antibody Microarray PCS248 analysis of COL6A1 silencing, the JAK2-STATs pathway was the most significantly changed." (PMID 25895032, 2015). "Of these genes, we selected TSPAN8, BST2, BMP7, and Col6A1 for further analysis, because these genes have been reported to be involved in tumorigenicity or cancer cell invasion and migration." (PMID 25221999, 2014). "Interestingly, the Carcinoma 3 cluster with high expression of COL6A1 and ITGA5 was predominantly observed in SCC." (PMID 40776410, 2025). "Among COL6A members, COL6A1/2/3 were predicted poor prognosis in specific cancers." (PMID 36167487, 2022). "Furthermore, we explored the relationship between COL6A1/2/3 and stem cell-like characteristics of 33 cancer types based on mRNA expression and stemness scores." (PMID 36167487, 2022). "Stromal cells (or cancer-associated cells) included endothelial cells (PECAM1/CD31+ and MMRN1+), fibroblasts (COL6A1+, COL1A1+, THY1+, and DCN+), epithelial cells (LAMC2+, KRT5+, and KRT14+), and unassigned name cells (high heat shock proteins expression), suggesting that they were cancerous cells." (PMID 35742914, 2022). "Moreover, we found that there were differences between expression levels of COL6A1/2/3 and DNAss in various cancer types." (PMID 36167487, 2022). "In colitis-associated cancer (CAC) models, mice with Col6a1+ fibroblast-specific deletion of Stat3 or Ikbkb (but not Tlr4 or Myd88) demonstrate reduced cancer development." (PMID 36591258, 2022). "In addition, the expression of COL6A1/2/3 was significantly related to drug sensitivity of cancer cells." (PMID 36167487, 2022). "In addition, offering extracellular collagen VI in Matrigel plugs rescued the ability of Col6a1-depleted cancer cells to invade within Matrigel." (PMID 36546396, 2022). "However, COL6A1 has been shown to stimulate proliferation and prevent apoptosis of cancer cells, which has also been found to be related to different types of cancers." (PMID 36357874, 2022). "Finally, our study revealed that COL6A1/2/3 expression was mainly negatively correlated with gene methylation, and the methylation levels showed remarkable differences in various cancers." (PMID 36167487, 2022). "Moreover, rescued expression of Col6a1 in Six1−/− MCA205 cancer cells was sufficient to abolish the CD8+ T cell infiltration induced by Six1 deletion." (PMID 34782761, 2021). "In the ascites-derived cancer cells, COL6A1-6A3 expression was relatively low (n = 4)." (PMID 34162871, 2021). "WT and Col6a1−/− MCA205 cancer cells were subcutaneously transplanted into C576BL/6N or nude mice." (PMID 34782761, 2021).
cancer (continued). "COL6A1 may play an important role in the metastatic process and could be considered a predictor of poor outcomes in several cancers." (PMID 34966737, 2021). "Preliminary classification of the identified antigens based on their differential expression both in the cancer antigen array and shotgun proteomics experiment showed that of these 5 antigens, only COL6A1, FGFR2 and CALM1 demonstrated promise as biomarkers of PCa by both approaches." (PMID 26885621, 2016). "However, a detailed characterization of Col6a1+ cells in cancer is still missing." (PMID 38203319, 2023). "In addition, in this study, aberrant methylation of COL6A1/2/3 was observed in some cancers, suggesting that abnormal expression of COL6A1/2/3 may be regulated by methylation modification in specific tumors." (PMID 36167487, 2022). "Collectively, we propose that COL6A1 and ITGA5 expression in SCC enhances adhesion to the ECM, thereby promoting the malignancy of the cancer." (PMID 40776410, 2025). "The proportion of Carcinoma 3 significantly increased within the carcinoma in cSCC compared to BCC with specific expression of ITGA5 and COL6A1 in SCC." (PMID 40776410, 2025). "Further, COL1A1, COL1A2, COL6A1, COL6A3, and SDC1 were upregulated in late-stage compared with early-stage patients in four cancer types." (PMID 38002057, 2023). "In pan-cancer analysis, SHOX2 expression positive correlated with CDKN2C (R = 0.41), COL6A1 (R = 0.35), COL6A2 (R = 0.37), DCHS1 (R = 0.37), MAPK7 (R = 0.34), PRRX1 (R = 0.37), RAB23 (R = 0.36) and RSRC1 (R = 0.36) via GEPIA2." (PMID 37170390, 2023). "Within collagen genes represented in this subset (9/15), we found that all the three main COL6 genes (COL6A1, COL6A2, COL6A3) displayed an increased expression in malignant tumors, with a significant and consistent overexpression in GBM." (PMID 37505240, 2023). "Although the three strands of the collagen VI isoforms (COL6A1, COL6A2 and COL6A3) were more abundant in the cancer matrix compared to the healthy matrix in the irradiated groups, these differences were not significant in our Volcano Plots." (PMID 35897841, 2022). "Further analysis found that COL6A1 and COL6A2 were relatively highly expressed in all cancer types compared with other COL6A members." (PMID 36167487, 2022). "In contrast, genes in neural (CDS1 and CHD4) and cancer-related (BTG1, COL6A1, PMP22 and HIF1A) pathways were increased by STAT3-KD, and their expression was reduced by STAT3 expression." (PMID 29774125, 2018). "COL11A1, COL6A1, MMP2, NID1, and FLT4 have been shown to have a positive role in regulating motility and invasion of various cancer cells." (PMID 28555007, 2017). "At the same time, multiple collagen-related genes (COL6A2, COL3A1, COL4A1, and COL4A2) in the MSC-2 cluster were upregulated in bone metastases, which is consistent with our observation of IGFBP3, TAGLN, LUM, COL6A1, COL6A2, and COL3A1 in pan-cancer in Fig. (1d)." (PMID 39156727, 2024). "CC-3 represented the mesenchymal-like cancer cell subpopulation that expressed mesenchymal genes such as Prrx1, Col6a1, Thy1, and Vim, but not epithelial marker genes such as Epcam and Cdh1." (PMID 37190324, 2023). "Upregulation of COL6A1, which is an extracellular matrix protein, has been reported to enhance motility and metastasis in some cancers, but there is no data on its effect in HVB-related HCC." (PMID 37685904, 2023). "We found a consistent positive correlation between fibroblast proportions and expression of collagen genes belonging to fibril-forming (COL1A2) and microfibrillar (COL6A1, COL6A2 and COL6A3) subfamilies across nine cancer types, the exception being KIRC and LGG." (PMID 36321857, 2022). "Thus, we speculated that COL6A1 could be transferred from OS cells to MRC5 cells via exosomes, vital mediators between cancer cells and the stroma to transfer genetic messages." (PMID 33391546, 2021).
myopathies (30 papers, 2011 to 2025). "The induction of mutations in exon 9 of COL6A1 in Zebrafish results in a more severe and early onset myopathy than that observed in mice, as well as mitochondrial dysfunction and cell death." (PMID 37686358, 2023). "To compare, a patient with a genetically confirmed COL6A1-associated myopathy was included: note the pronounced degeneration and atrophy of the distal vastus lateralis and medial gastrocnemius muscles, which is similarly found in p7 (arrows)." (PMID 37047781, 2023). "We aimed to use the Col6a1 null mouse strain as a model to study the role of collagen VI in the pathogenesis of skin abnormalities associated with collagen VI related myopathies." (PMID 25158062, 2014). "For example, Col6a1–deficient and Col15a1-deficient mice have a muscle phenotype that strongly resembles human myopathies." (PMID 21909251, 2011). "In the last two decades, much effort was spent on the elucidation of the pathogenic mechanisms underlying ColVI‐related myopathies, also by taking advantage of the ColVI null (Col6a1−/−) mouse model, in order to identify druggable targets for prospective therapies." (PMID 38984773, 2024). "Mutations in COL6A1-3 genes cause a spectrum of COL6-related myopathies." (PMID 34888314, 2021). "The beneficial effects of spermidine administration in col6a1−/− mice are associated with its ability to reactivate the autophagic flux, a process which is overtly impaired in this animal model as well as in the corresponding human myopathies." (PMID 26565691, 2015). "Mice null in collagen VI through homozygous knockout of the COL6A1 gene display histological features of myopathy including muscle fibre necrosis and phagocytosis." (PMID 37686358, 2023). "Spontaneous myofiber apoptosis is a typical feature of COL6-related myopathies and its amelioration is beneficial both in Col6a1–/– murine model and in BM and UCMD patients." (PMID 33134297, 2020). "Recent studies in col6a1 null mice and patients' biopsies provided novel insights into the molecular mechanisms underlying COL6-related myopathies." (PMID 27656840, 2016). "COL6A1 mice, a COLVI null model, and COL6A3 deficient mice develop a mild myopathy and tendon dysfunction possibly due to altered tendon fibrillogenesis." (PMID 27375477, 2016). "Our data suggest that LPD in human COL6 myopathies recapitulates the beneficial effects seen in col6a1 null mice." (PMID 27656840, 2016). "Here we evaluated if Col6a1 null mice, an established animal model for the muscle changes in collagen VI related myopathies, are also suitable for the study of mechanisms leading to the skin pathology." (PMID 25158062, 2014). "This indicates that although Col6a1 null mice do not display an overt wound healing defect, some features seen in skin of collagen VI related myopathy patients are also present in Col6a1 null mice." (PMID 25158062, 2014). "This study investigated protein alterations in three muscles (gastrocnemius, tibialis anterior and diaphragm) of Col6a1−/− mice, a model of human collagen VI myopathies." (PMID 23437220, 2013). "This study for the first time identifies and correlates alterations in proteins involved in the metabolism and mechanotransduction in three muscles of Col6a1−/− mice, a model of human collagen VI myopathies." (PMID 23437220, 2013). "This study identifies metabolic and protein phenotypic alterations in gastrocnemius, tibialis anterior and diaphragm muscles of Col6a1−/− mice, a model of human collagen VI myopathies." (PMID 23437220, 2013). "These muscles were selected since they are differently affected in Col6a1−/− mice and in human collagen VI myopathies." (PMID 23437220, 2013). "The first clue of a therapeutic approach for COL6-related myopathies came from evidence that mitochondrial dysfunction triggers the apoptosis of myofibers and medication and that autophagy is impaired in Col6a1-/- mice as well as in UCMD patients." (PMID 34888314, 2021).